METTL5 (methyltransferase 5, N6-adenosine)
Diseases named in the same sentence as METTL5 in open-access papers (continued):
Sharing a sentence is not in itself a finding about the gene and the disease.
tumor (20 papers, 2020 to 2026). "METTL5 promotes anti-tumor immune function and inhibits tumor-associated immune escape in PBMCs cells." (PMID 41194259, 2025). "However, both METTL5‐KO human and murine tumor cells display increased susceptibility to T cell‐mediated killing when compared with corresponding control cells." (PMID 41042068, 2025). "Reduced ATF4 translation in METTL5‐deficient OC cells enhances tumor ferroptosis." (PMID 41042068, 2025). "By pretreating OC cells with Ferrostatin‐1, a ferroptosis inhibitor, METTL5‐KO OC cells showed similar sensitivity to killing induced by paired tumor‐reactive T cells as control tumor cells." (PMID 41042068, 2025). "In vitro experiments, we demonstrated that METTL5 promotes tumor progression in LUSC via CCK-8, colony formation assay, transwell migration assay, and wound healing assay." (PMID 40018408, 2025). "At the disease level, METTL5’s role in the tumor immune microenvironment remains largely unexplored." (PMID 41487998, 2025). "Next, we further explored the function of METTL5 in LUSC, the results showed older age, gender, and tumor stage were positive with METTL5 expression level." (PMID 40018408, 2025). "METTL5 is frequently upregulated across multiple malignancies and promotes tumor development through various mechanisms." (PMID 41487998, 2025). "Rescue experiments further demonstrated that Myc overexpression counteracted the suppressive effects of METTL5 knockdown on PD-L1 and tumor cell malignancy." (PMID 41487998, 2025). "During the observation of flank xenografts in BALB/c nude mice for 28 days, METTL5 knockdown significantly decreased tumor volume compared with that of control tumors." (PMID 40018408, 2025). "An integrative analysis combining in vitro genome‐wide immune screens, in vivo ICB screens, and clinical data mining identifies METTL5 as a key tumor‐intrinsic immune factor." (PMID 41042068, 2025). "Accumulating evidence has indicated that METTL5 is highly expressed and promotes tumor progression, however, the role of METTL5 in LUSC is not explored." (PMID 40018408, 2025). "Collectively, these findings establish METTL5 as a pivotal modulator of tumor immunity and a potential therapeutic target for overcoming immune resistance." (PMID 41487998, 2025). "Combined METTL5 targeting using lipid nanoparticle-encapsulated siRNA and PD-1 blockade provokes anti-tumor immunity to eradicate ICC tumors." (PMID 41431992, 2025). "The correlations between METTL5 expression and clinical properties were evaluated in the TCGA dataset, we found that METTL5 expression level was positive with older age, gender, and tumor stage." (PMID 40018408, 2025). "Methyltransferase 5 (METTL5) catalyzes 18S rRNA N6‐methylation at adenosine 1832 (m6A1832) and overexpression of METTL5 in a mouse xenograft model resulted in tumor growth." (PMID 40448344, 2025). "In summary, accumulating evidence highlights METTL5 as a critical regulator of tumor immunity through multiple mechanisms." (PMID 41487998, 2025). "Since IFNγ is one of the major immune stimulants that induce tumor cell stress, our results suggest that METTL5 continues to regulate ATF4 translation in OC cells even under the immune attack." (PMID 41042068, 2025). "Immunofluorescence results of HL‐60 cells cocultured with HL‐60 cells from METTL5‐sh and METTL5‐NC groups showed MPO/H3 expression in METTL5‐NC group was higher than METTL5‐sh group, consistent with tumor tissue results." (PMID 38613157, 2024). "Our cellular experiments demonstrated that high METTL5 expression in HCC led to malignant tumor cell behavior and poor patient prognosis." (PMID 38613157, 2024). "METTL5 is a novel m6A modification methyltransferase that frequently participated in the tumor cancerous progress." (PMID 39261486, 2024). "Further analyses were adopted for assessing METTL5 gene expression in relation to tumor stage, and the METTL5 gene expression gradually increased among the advent of HCC progression via GEPIA." (PMID 37400463, 2023).
tumor (continued). "The oncogenesis and development of HCC are closely related to METTL5 expression, and the overexpression of METTL5 resulted in the poor survival outcome of HCC patients by regulating tumor immune microenvironment." (PMID 37400463, 2023). "The possible correlation of METTL5 with the tumor-related infiltration of immune cells for HCC were explored comprehensively by using the online tools of TIMER and TISIDB." (PMID 37400463, 2023). "Recent studies emphasized that METTL5 stimulated the proliferation and invasion activity of tumor cells in pancreatic cancer." (PMID 37400463, 2023). "Recent studies revealed that METTL5 functioned as an oncogene that produced a marked effect on the hyperactivation of tumor cell proliferation, migration, and invasion." (PMID 37400463, 2023). "METTL5 overexpression affects the carcinogenic effect by taking part in the regulation of tumor immunity." (PMID 37400463, 2023). "In our study, knocking down METTL5 weakened proliferation, reduced tumor volume and biomarker levels, and increased apoptosis." (PMID 35166644, 2022). "METTL5 expression in UCEC tumor tissue increased, and with high METTL5 isoform expression, patients with UCECs had poor prognostic outcomes." (PMID 35166644, 2022). "We knocked down METTL5 levels using a lentivirus to explore the role of METTL5 in apoptosis and tumor progression in EC." (PMID 35166644, 2022). "METTL5 is a methyltransferase that catalyzes the m6A modification of 18S rRNA, a process known to enhance the translational efficiency of several oncogenic proteins and thereby promote tumor development." (PMID 41551838, 2026). "Collectively, these findings suggest that METTL5 may act as a key modulator of the tumor immune landscape." (PMID 41487998, 2025). "Considering the context-dependent activity of METTL5, future drug development should prioritize stratification of METTL5-dependent tumor subtypes, leveraging CRISPR gene dependency data, compound sensitivity profiles, and single-cell transcriptomics to enable precision targeting." (PMID 41487998, 2025). "Besides, in the in vivo mice xenograft assay, the METTL5 silencing reduced the tumor growth (volume)." (PMID 39261486, 2024). "Tumor growth rate and weight significantly decreased upon METTL5 downregulation versus control." (PMID 38613157, 2024). "Marker genes of tumor immune-infiltrated cells have strong connection with METTL5." (PMID 37400463, 2023). "Furthermore, knocking down METTL5 weakened the proliferation, reduced tumor volume and biomarkers, and increased apoptosis." (PMID 35166644, 2022). "Some regulators functioned as tumour suppressors, including METTL5, YTHDC2, and G3BP1." (PMID 34802443, 2021). "Since prediction power of single gene was still insufficient, in order to further optimize the prediction power, we further screened four genes that have great correlation with the METTL5 gene and have predictive value for tumor prognosis through multiple machine learning algorithm." (PMID 33679869, 2020). "Consequently, METTL5 KO enhances tumor sensitivity to T cell‐mediated antitumor immunity." (PMID 41042068, 2025). "METTL5 may influence the translation of key immune modulators, including cytokines, co-stimulatory molecules, or immunosuppressive factors, thereby affecting immune infiltration, anti-tumor immunity, and immunotherapy responsiveness." (PMID 41487998, 2025). "Collectively, METTL5 represents a highly complex and multilayered regulatory node, with functions spanning classical rRNA modification and translational control to phase separation, chromatin architecture, immune microenvironment regulation, and tumor heterogeneity." (PMID 41487998, 2025). "Importantly, METTL5 expression was strongly correlated with immune scores, stromal scores, and infiltration levels of 25 immune cell subsets, indicating that METTL5 may promote RCC progression by remodeling the tumor immune microenvironment (TIME)." (PMID 41487998, 2025).
tumor (continued). "Notedly, overexpression METTL5 promoted LUSC tumorigenesis in an m6A modification, while METTL5 knockdown markedly inhibited proliferation and migratory ability of tumor cells in vitro and in vivo." (PMID 40018408, 2025). "Mechanistically, METTL5 maintained NRF2 mRNA stability in an m6A-dependent manner via the reader protein IGF2BP1, forming a METTL5/m6A/NRF2 axis that inhibited Fe2+ accumulation, ferroptosis, and T cell–mediated tumor killing." (PMID 41487998, 2025). "Instead, our multiomic analyses indicate that METTL5 modulates immune resistance via ATF4, revealing a previously unrecognized pathway linking rRNA methylation to tumor immune evasion." (PMID 41042068, 2025). "Next, we performed in vivo experiments utilizing METTL5 knockdown (shMETTL5-1) and control RPMI-8226 cells to construct MM blood tumor models." (PMID 40750759, 2025). "Our experiments suggest METTL5 has an important regulatory role in promoting neutrophil activation and NET formation/release in tumor immunity." (PMID 38613157, 2024). "Results show that METTL5 expression in UCEC tumor tissue was increased, and UCEC patients with high METTL5 expression had worse prognostic outcomes." (PMID 35166644, 2022). "In addition, METTL5 suppresses ferroptosis by stabilizing antioxidant factors including NRF2, SLC7A11, and UBE3C, thereby facilitating tumor immune evasion." (PMID 41487998, 2025). "Further analyses suggested that METTL5 was an independent prognostic factor and its prognostic value was not affected by tumor stage." (PMID 33679869, 2020). "The methylation level of METTL5 gene 1st Exon and TSS1500 in tumor tissues is significantly lower than that in normal lung tissue, which suggests that these two sites may involve in the aberrant expression of METL5." (PMID 33679869, 2020). "The overall survival of patients with low METTL5 expression is better than that of patients with high expression regardless of tumor stage." (PMID 33679869, 2020). "However, Mettl5 KO in murine OC cells did not reduce IFNγ production by tumor‐reactive CD8+ T cells after tumor stimulation, suggesting that loss of Mettl5 minimally affects immune synapse formation between CD8+ T cells and tumors." (PMID 41042068, 2025). "At the same time, we have discovered that METTL5 in HCC may be involved in the regulation of tumor immunity, which has not been reported before." (PMID 38613157, 2024). "Combining the results of the METTL5 gene RNA-seq with gene mutation and CNV data, the results suggested that METTL5 gene mutations were not common in tumor tissues, and CNV amplification might play a role." (PMID 33679869, 2020). "In addition, METTL5 expression is a significant prognostic factor regardless of tumor stages." (PMID 33679869, 2020).
genetic disorders (1 paper, 2026). "Despite METTL5's clinical relevance, the molecular mechanisms underlying METTL5-related genetic disorders remain poorly understood." (PMID 42100868, 2026).
infection (1 paper, 2023). The state of being infected such as from the introduction of a foreign agent such as serum, vaccine, antigenic substance or organism. "We also confirmed that increased METTL5 mRNA expression was strongly linked with unfavorable OS and PFS in stage 3, stage 3 + 4, AJCC T3, drinking alcohol hobby, no infection with Hepatitis virus diseases, and male HCC patients." (PMID 37400463, 2023).
neurodevelopmental disorder (1 paper, 2025). A behavioral and cognitive disorder with onset during the developmental period that involves impaired or aberrant development of intellectual, motor, or social functions. "While we detail here the genetic and epigenetic mechanisms of Pvt1 ME and its functional consequence, there are several aME genes from our list that are associated with neurodevelopmental disorders, such as Grik3, Mettl5, Gap43, and Tubb3." (PMID 41223055, 2025).
METTL5 also shares sentences with these, for which no sentence is quoted: atherosclerosis (1 paper); attention deficit-hyperactivity disorder (1); breast invasive carcinoma (1); colon carcinoma (1); colorectal cancer (1); developmental delay (1); glioma (1); heart disease (1); hypertrophy (1); lung carcinoma (1); lung squamous cell carcinoma (1); lymph node metastasis (1); metabolic disorders (1); myopia (1); neurological diseases (1); oligoasthenoteratozoospermia (1); Parkinson disease (1); recessive intellectual disability (1); speech delay (1); thymoma (1).